EPHA2 (EPH receptor A2)
Diseases named in the same sentence as EPHA2 in open-access papers (continued):
Sharing a sentence is not in itself a finding about the gene and the disease.
bladder cancer (21 papers, 2018 to 2025). "The subsequent research also shows that EVs-EphA2, which promotes the proliferation, invasion, and migration of bladder cancer cells, exhibits strong diagnostic performance, with a sensitivity of 61.1% and a specificity of 97.2%." (PMID 40078996, 2025). "EphA2 expression in patients with bladder cancer is prevalent and is associated with later stage metastatic disease; however, its prognostic relevance remains largely unclear." (PMID 33092175, 2020). "Relative to non-bladder cancer patients, the AUC receiver–operator curve for urinary EV EphA2 was 0.79, indicating the promising accuracy of this test." (PMID 39682778, 2024). "As recently shown, progranulin is highly expressed in bladder cancer cells and is the prevalent ligand for EphA2, thereby constituting an oncogenic pathway driving motility, invasion, and in vivo tumor formation of bladder cancer cells." (PMID 39596256, 2024). "In another study, a novel EphA2-targeting antibody-directed nanotherapeutic, encapsulating a labile prodrug of docetaxel (EphA2-ILs-DTXp), was developed to treat EphA2- expressing bladder cancers." (PMID 39596256, 2024). "In a study of 49 patients with bladder cancer and 48 healthy donors as controls, EVs purified from the urine of patients were significantly enriched with EphA2." (PMID 39682778, 2024). "For instance, circRNA 001418 facilitates the invasion and metastasis of bladder carcinoma by regulating the miR-1297/EphA2 axis." (PMID 37079240, 2023). "An important step forward in deciphering progranulin oncogenic mechanisms of action was the identification of EphA2 as the functional progranulin receptor in bladder cancer." (PMID 36980592, 2023). "In bladder cancer, progranulin action relies on the activation of its functional signaling receptor EphA2." (PMID 36980592, 2023). "Our group has recently demonstrated that in bladder cancer progranulin oncogenic activity relies on EphA2, which is the progranulin functional receptor in this tumor model." (PMID 36471440, 2022). "EphA2 is the key mediator of progranulin signaling in bladder cancer where progranulin did also modestly activate EGFR, EphA4 and EphB2." (PMID 36471440, 2022). "Recent data from our laboratories have demonstrated that progranulin and its receptor, EphA2, constitute an oncogenic pathway in bladder cancer by promoting motility, invasion and in vivo tumor formation." (PMID 36471440, 2022). "In bladder cancer, Beibei Liu has proved that EPHA2 can promote the growth and metastasis of cancer cells by activating the PI3K/AKT signaling pathway." (PMID 35410462, 2022). "We recently provided a significant advance in the field by identifying a functional membrane receptor for progranulin, EphA2, and later demonstrated that the progranulin/EphA2 is a critical oncogenic axis in bladder cancer." (PMID 36471440, 2022). "We previously demonstrated that EphA2 is the signaling receptor activated by progranulin in bladder cancer." (PMID 36471440, 2022). "In bladder cancer, EphA2 activation by progranulin mediates progranulin-dependent activation of AKT and MAPK pathways, thereby sustaining EphA2 phosphorylation at S897." (PMID 36471440, 2022). "In bladder cancer cells progranulin stimulated Akt- and Erk1/2-mediated EphA2 phosphorylation at Ser897 and EphA2 depletion attenuated proliferation and cisplatin resistance, mimicking progranulin depletion." (PMID 33572284, 2021). "Liprin-α1 is abundantly expressed in several bladder cancer cell lines and it strongly co-localizes with EphA2 upon progranulin stimulation." (PMID 34654889, 2021). "Pull-down experiments in human bladder cancer cell line T24 showed that liprin-α1 binds to EphA2 and promotes progranulin-dependent motility." (PMID 34654889, 2021). "EphA2 expression was detected in 80–100% of bladder cancer samples and correlated with shorter patient survival." (PMID 33092175, 2020).
bladder cancer (continued). "Here, we show that EphA2 is an attractive target for molecular targeting in bladder cancer, and we demonstrate the preclinical activity of an EphA2-targeted ADN." (PMID 33092175, 2020). "EphA2 is a promising target for the treatment of bladder cancer, since this receptor is strongly expressed in both primary and metastatic tumors." (PMID 33092175, 2020). "Our work demonstrates that targeting EphA2 in bladder cancer with the EphA2-ILs-DTXp ADN produces significantly better results than docetaxel alone." (PMID 33092175, 2020). "The EphA2 expression pattern in bladder cancer suggests that EphA2-ILs-DTXp would efficiently target metastatic urothelial carcinomas." (PMID 33092175, 2020). "To test the activity of EphA2-ILs-DTXp in EphA2-expressing bladder cancer, we performed in vivo experiments in mice carrying subcutaneous bladder cancer tumors." (PMID 33092175, 2020). "For the treatment of bladder cancer and other solid tumors, we developed an EphA2-targeted ADN encapsulating a novel docetaxel prodrug, DTXp." (PMID 33092175, 2020). "These particles were effective in multiple EphA2-positive bladder cancer models, either as monotherapy or in combination with gemcitabine." (PMID 33092175, 2020). "Animals bearing three EphA2-positive PDX models of bladder cancer (BL-0293, BL-0382, BL-0440) were treated with four weekly doses of gemcitabine, EphA2-ILs-DTXp, or their combination." (PMID 33092175, 2020). "Furthermore, EVs purified from highly EphA2-expressing bladder cancer cells significantly increased the invasiveness of U-BLC1 bladder cancer cells as assessed by Matrigel invasion assay, whereas the knockout of EphA2 inhibited this invasion-promoting effect." (PMID 39682778, 2024). "In bladder cancer, Chu and Zhang showed that EFNA1 could causd the internalization and downregulation of EPHA2 on endothelial cells, leading to the activation of angiogenesis." (PMID 37160815, 2023). "Notably, in this tumor model, progranulin sustains AKT and MAPK activation and the phosphorylation of EphA2 at Ser 897, as in bladder cancer cells." (PMID 36980592, 2023). "Our analysis of 20 samples of surgically resected bladder cancer shows that the vast majority of tumors overexpressed EphA2 on more than 10% of tumor cells and that the majority of these urothelial carcinomas also express EphA2 on the tumor vasculature." (PMID 33092175, 2020). "The EphA2-targeted antibody-directed nanotherapeutic EphA2-ILs-DTXp controlled tumor growth, mediated greater regression, and was more active than free docetaxel at equitoxic dosing in all four EphA2-positive bladder cancer PDX models." (PMID 33092175, 2020). "Here, we report the results of studies characterizing EphA2 expression in bladder cancer." (PMID 33092175, 2020). "The activity of EphA2-ILs-DTXp in combination with gemcitabine was compared to the combination of equitoxic dosing of free docetaxel with gemcitabine in an additional EphA2-positive bladder cancer model (BL417362)." (PMID 33092175, 2020). "Our data highlight the prognostic value of EphA2 in bladder cancer as well as the therapeutic potential of the EphA2-targeting antibody-directed nanotherapeutic EphA2-ILs-DTXp, supporting its clinical exploration as a novel targeted therapy for the treatment of urothelial carcinoma." (PMID 33092175, 2020). "PGRN was found to replace the typical ligand of EphA2-A1 in bladder cancer, phosphorylation of EphA2 Ser897 induced by PGRN binding to EphA2 might induce crosstalk between other receptor tyrosine kinases, including other Eph receptors and epidermal growth factor receptor (EGFR)." (PMID 37660003, 2023). "One study found that ephrin type-A receptor 2 (EphA2) was prominently upregulated in urinary EVs, and EV-EphA2-CD9 ELISA performed well in diagnosing early bladder cancer." (PMID 37907962, 2023).
bladder cancer (continued). "In particular, recent studies have shown that EPH receptor A2 (EphA2) and drebrin, an F-actin binding protein, play essential roles in progranulin derived, Akt/ERK proteins mediated signal transduction in bladder cancer." (PMID 33490663, 2021). "Through selective reaction monitoring/multi-reaction monitoring (SRM/MRM), EphA2 on urinary EVs presents significant expression differences between patients with bladder cancer/non-malignant hematuria and healthy controls." (PMID 40078996, 2025). "What’s more, exosomal miR-93-5p suppressed BTG2 expression and promoted bladder cancer cells progression, exosomal EphA2 promoted the invasion and migration of bladder cancer cells, exosomal CDC6 effectively repressed the malignant process of bladder cancer cells." (PMID 37805491, 2023). "In bladder cancer cells, progranulin binds to and activates ephrinA1-independent EphA2 non-canonical signaling favoring tumor progression, while in the neuron-like cell line NSC-34, progranulin binds to RET and promotes its tyrosine-phosphorylation." (PMID 36980592, 2023). "Contrary to our previous data in bladder cancer, our results suggest that EphA2 is not the main functional progranulin signaling receptor in mesothelioma." (PMID 36471440, 2022). "Especially, EphA2 and drebrin, an F-actin binding protein, play an essential roles for progranulin derived cancer promoting functions via phosphorylation of Akt and ERK proteins in bladder cancer." (PMID 33490663, 2021). "We surveyed EphA2 expression in both primary and metastatic disease, evaluated its prognostic value, and tested the in vivo activity of EphA2-ILs-DTXp (as a monotherapy and in combination with gemcitabine) in EphA2-positive patient-derived xenograft (PDX) models of bladder cancer." (PMID 33092175, 2020). "The interaction between Progranulin and EphA2 triggers transient phosphorylation of Y588 on EphA2, which then activates AKT/ERK kinases, thereby generating a feedback mechanism promoting EphA2 phosphorylation at S897, driving tumor progression in bladder cancer." (PMID 39596256, 2024). "Thus, EphA2-ILs-DTXp could represent a promising combination partner not only with other chemotherapies, but also with anti-PD1/PD-L1 drugs in bladder cancer." (PMID 33092175, 2020).
nasopharyngeal carcinoma (21 papers, 2015 to 2026). A carcinoma arising from the nasopharyngeal epithelium. "Here, we report that PRMT5 bound to EphA2, catalyzed the dimethylation of EphA2 at arginine 816, and then stabilized EphA2 via inhibiting Cbl-mediated EphA2 ubiquitination and degradation in nasopharyngeal carcinoma (NPC) cells." (PMID 41930341, 2026). "Ephrin A family members that are overexpressed in cancer including EFNA1 in melanoma; EPHA2 in prostate cancer, nasopharyngeal carcinoma, and squamous-cell carcinoma of the head and neck; and EPHA3 in non-small-cell lung cancer." (PMID 33977106, 2021). "HDAC7 was reported to enhance EphA2 expression by downregulating miR-4465 expressing, showing a positive effect on tumour proliferation, migration, and invasion in nasopharyngeal carcinoma (NPC)." (PMID 34395273, 2021). "EPHA2 regulates the sensitivity to paclitaxel in nasopharyngeal carcinoma via the phosphoinositide 3-kinase/Akt signaling pathway." (PMID 33977106, 2021). "Accordingly, inhibition of the c-Cbl-EphA2 interaction, due to molecular competitors such as the Ca2+ or phospholipid-binding protein Annexin A1 (ANXA1), increases EphA2 protein stability and promotes nasopharyngeal carcinoma in vitro and in vivo growth and metastasis." (PMID 39596256, 2024). "Moreover, the Py772- EPH Receptor A2 (EphA2) oncoprotein has been described to induce proliferation and anchorage-independent growth and tumorigenicity in vivo in nasopharyngeal carcinoma cell lines in a GAB1-dependent manner." (PMID 37627207, 2023). "ANXA1 also binds and stabilizes EphA2 to promote nasopharyngeal carcinoma growth and metastasis." (PMID 36678567, 2023). "Additionally, ANXA1 targeting could be useful, considering that it promotes the progression and metastasis of nasopharyngeal carcinoma through the stabilization of ephrin type-A receptor 2 (EphA2), and that exosomal ANXA1 is driving the malignant transformation of thyroid cells in thyroid cancer." (PMID 41283264, 2025). "Phosphorylation of EphA2 at S897 mediates the activation of the AKT, STAT3, SOX-2, and c-MYC signaling pathways, which is crucial to nasopharyngeal carcinoma stem cell formation." (PMID 37063424, 2023). "Studies have shown that EphA2 pS897 activates the AKT, STAT3, SOX-2, and c-MYC signaling pathways and plays a crucial role in nasopharyngeal carcinoma stem cell formation." (PMID 37063424, 2023). "In 2018, two independent papers determined EPHA2 as the EBV entry receptor in a variety of cancer cell lines including the gastric adenocarcinoma epithelial cell line AGS and the nasopharyngeal carcinoma cell lines CNE1, CNE2 and HNE1." (PMID 33596248, 2021). "In nasopharyngeal carcinoma (NPC), MFSD4A-recruited RNF149 mediates the ubiquitination and degradation of EPHA2, thus inhibiting the proliferation, migration, and invasion of NPC cells." (PMID 37958377, 2023).
non-small cell lung carcinoma (19 papers, 2011 to 2025). A group of at least three distinct histological types of lung cancer, including non-small cell squamous cell carcinoma, adenocarcinoma, and large cell carcinoma. "Here, we investigate the effects of tumor-specific EphA2 on the anti-tumor immune response in mouse models of non-small cell lung cancer." (PMID 40867322, 2025). "In non-small cell lung cancer, EphA2 reduces progression-free survival and overall survival of patients." (PMID 37980165, 2023). "EphA2 was shown also to promote growth, invasion, and survival of non-small-cell lung cancer (NSCLC) stem cell-like populations (enriched for the Aldehyde Dehydrogenase activity, ALDH) by increasing the levels of p-JNK." (PMID 33572284, 2021). "This study also suggests that a combination of doxazosin and other EPHA2 inhibitors directed to inhibit the pertinent signaling components may be a novel therapeutic strategy for MPM and Non-small cell lung cancer patients who have either EPHA2 or CBL alterations." (PMID 31484920, 2019). "For example, in non-small cell lung cancer, JNK signaling mediates ephrin type-A receptor 2 (EPHA2)-dependent tumor cell proliferation and motility." (PMID 40509244, 2025). "An EphA2 tyrosine kinase inhibitor has been shown to induce tumour regression in human non-small cell lung cancer (NSCLC) xenografts in vivo, indicating that EphA2 is a promising molecular target in cancer therapy." (PMID 26158630, 2015). "IP and PLA have demonstrated a physical interaction between EphA2 and VEGFR2 in non-small cell lung carcinoma cells which promotes tumor cell migration and cancer invasiveness; when phosphorylation of serine (S) 897 of EphA2 is prevented these activities are impaired." (PMID 35096972, 2021). "Conversely, we previously demonstrated that EphA2 inhibition could attenuate the malignant cellular behavior of RCC cells in vitro, similar to previous in vitro results against cellular migration and invasion in non-small-cell lung cancer." (PMID 41440001, 2025).
Age-related cataract (18 papers, 2008 to 2024). A type of cataract (opacification of the lens) that forms during the course of aging. "Variants in the genes for ephrinA1 (EFNA1) and ephrinA5 (EFNA5), which encode known ligands of EPHA2, have also been associated with age-related cataract but only EFNA1 reached genome-wide significance." (PMID 38927721, 2024). "Association of only EPHA2 gene with age-related cataracts has been studied in different populations including Chinese and Indians." (PMID 37651414, 2023). "At least 8 genes are known to be directly associated with age-related cataracts, including EPHA2, GJA8, GALT, SLC16A12, HSF4, GALK1, FTL, and CRYAA." (PMID 36107580, 2022). "A non-coding risk allele for age-related cataract (rs6603883) located in a paired-box-2 (PAX2) binding-site within the EPHA2 gene promoter suggested that it acts by down-regulating EPHA2 expression in cultured lens cells." (PMID 34685586, 2021). "EPHA2 is a transmembrane tyrosine kinase receptor that, when disrupted, causes congenital and age-related cataracts." (PMID 33671840, 2021). "We therefore believe that the polymorphism rs3754334 of the EPHA2 gene is truly associated with the risk for the development of age-related cataract across populations of different ethnic/racial backgrounds." (PMID 23976972, 2013). "The EPHA2 gene has been also associated with age-related cataract, suggesting that intercellular junctions are important in not only lens development, but also in maintaining lens transparency." (PMID 23288986, 2012). "We found an association between the EPHA2 SNPs rs7543472 and rs1120867 with age-related cataracts in the Indian population." (PMID 22412971, 2012). "The association of EPHA2 with age-related cataracts in Caucasians prompted us to investigate its association with ARC in the Han Chinese population." (PMID 21686326, 2011). "Candidate gene association analysis further identified SNPs in the EPHA2 region of chromosome 1p that were suggestively associated with age-related cataracts (p=0.007 for cortical cataracts, and p=0.01 for cortical and/or nuclear cataracts)." (PMID 19005574, 2008). "Here, we further demonstrate that variations in the EPHA2 region are associated with age-related cortical cataracts (p=0.007), and age-related cataracts overall (p=0.01) in an Italian population." (PMID 19005574, 2008). "To investigate the possibility that EPHA2 was associated with age-related cataracts, we performed candidate-gene SNP allele association studies in a case-control cohort from Northern Italy." (PMID 19005574, 2008). "In conclusion, our data have associated EPHA2 with both inherited and age-related cataracts, and suggest that dysfunction of a member of the EphA-receptor tyrosine kinase sub-family triggers loss of lens transparency." (PMID 19005574, 2008). "Several nsSNPs in EPHA2 affect the stability and translational regulation of the protein and have been associated with congenital and age-related cataracts in humans." (PMID 35295853, 2022). "However, since rudimentary statistical analysis confirmed that somatic SNVs in EPHA2 were present at comparable frequencies in both clear lenses and those with age-related cataract we are unable to determine if such variants are causative for disease." (PMID 29267365, 2017). "It is hypothesized that the loss of EPHA2 function may directly or indirectly impair cellular structural stability, cell-to-cell crosstalk, protein folding, and transcriptional activation, which cause congenital or age-related cataract." (PMID 26664742, 2015). "Mutations in the EPHA2 (encodes for the receptor EphA2) and EFNA5 (encodes for the ligand ephrin-A5) genes have been linked to congenital and age-related cataracts in human patients." (PMID 39466050, 2024). "In particular, dysfunction of the receptor EphA2 or the ligand ephrin-A5 lead to a variety of congenital and age-related cataracts, defined as any opacity in the lens, in human patients." (PMID 35295853, 2022).